SNHG15 (small nucleolar RNA host gene 15)
Diseases named in the same sentence as SNHG15 in open-access papers (continued):
Sharing a sentence is not in itself a finding about the gene and the disease.
glioma (12 papers, 2020 to 2023). A benign or malignant brain and spinal cord tumor that arises from glial cells (astrocytes, oligodendrocytes, ependymal cells). "What interested us was that SNHG15 has been linked to chemoresistance such as temosolomide resistance in glioma and 5-FU resistance in colorectal cancer." (PMID 32655137, 2020). "In addition to SNHG15, abnormal expression of diverse lncRNAs has been implicated in glioma and medulloblastoma molecular pathology." (PMID 37880732, 2023). "Modulating SNHG15/CDK6/miR-627 axis by palbocicli could reduce M2-polarization of glioma-associated microglia in GBM multiforme and finally could overcome TMZ resistance." (PMID 34178658, 2021). "SNHG15 was highly expressed in glioma vascular endothelial cells and knockdown of the ncRNA inhibited proliferation, migration, and tube formation in vitro." (PMID 37056344, 2023). "The results of another study indicated that SNHG15 is highly expressed in glioma vascular endothelial cells (p < 0.05), while its knockdown suppressed cell proliferation, migration, and tube formation in vitro." (PMID 34771549, 2021). "Analysis based on different cancer types showed that SNHG15 has the most prominent prognostic potential in glioma (HR = 3.81; 95% CI, 0.84–42.69; P=0.28), and the results needed to be further supported by more high quality and large sample studies." (PMID 32633324, 2020). "Previous studies have found that SNHG15 expression contributes to cisplatin resistance in BC and temozolomide resistance in glioma." (PMID 32733556, 2020). "The analysis based on different cancer types showed that SNHG15 had the most prominent prognostic potential in Glioma (HR = 3.81; 95% CI, 0.84–42.69; P=0.28)." (PMID 32633324, 2020). "In the human medulloblastoma cell line DAOY, SNHG15 was modulated by EphrinA5-induced signal transduction, with EphrinA5 stimulation significantly reduced SNHG15 expression which might be relevant for the regulation of tumorigenic processes in the context of glioma." (PMID 37056344, 2023). "Therefore, SNHG15 and its target miR-153 could serve as new potential therapeutic targets for the antiangiogenic treatment of glioma through the downregulation of CDC42." (PMID 34771549, 2021). "Indeed, a recent study suggests that SNHG15 targets CDK6 in glioma." (PMID 34734088, 2021). "Mechanistically, SNHG15 elevated VEGFA and Cdc42 expression by sponging miR-451 at the post‐transcriptional level, facilitating the angiogenesis of glioma." (PMID 37056344, 2023). "Many lncRNAs had been elaborately discussed in this chemoresistance in glioma, such as LINC01198, SNHG15, and MALAT1." (PMID 33817241, 2020). "Likewise, small nucleolar RNA host gene 15 (SNHG15) lncRNA knockdown reduced the expression levels of pro-angiogenic factor cell division control protein 42 homolog (CDC42) and VEGF because the miR-153 was longer sponged and led to suppression of tumor angiogenesis in adult glioma cells." (PMID 37444408, 2023).
hepatocellular carcinoma (12 papers, 2017 to 2023). A malignant tumor that arises from hepatocytes. "Moreover, lncRNA SNHG15 was found to be associated with histological grade, tumor node metastasis stage (TNM) stage, and poor overall survival in hepatocellular carcinoma (HCC), suggesting its potential role as a novel biomarker in HCC patients." (PMID 29137412, 2017). "Furthermore, SNHG15 may serve as an efficient prognostic biomarker for hepatocellular carcinoma." (PMID 28720111, 2017).
lung cancer (12 papers, 2019 to 2025). A malignant neoplasm involving the lung. "SNHG15 can act on the biological functions of lung cancer and LUAD through different molecular mechanisms." (PMID 36864456, 2023). "In lung cancer, it has been reported that SNHG15 overexpression enhances tumour occurrence and development by targeting miRNA-211-3p to regulate cell proliferation and migration in vitro." (PMID 33243205, 2020). "SNHG15 (Small Nucleolar RNA Host Gene 15) is a well-studied oncogenic lncRNA that promotes cell proliferation, migration, and resistance to apoptosis in various cancers, including colorectal, breast, and lung cancer." (PMID 39969652, 2025). "Subgroup analysis showed that the high expression of SNHG15 was associated with a significantly poor OS of patients with digestive cancer (HR = 1.91, 95% CI = 1.38–2.66, P=0.0001), but not lung cancer (HR = 1.83, 95% CI = 0.89–3.76, P=0.010)." (PMID 32733556, 2020).
prostate carcinoma (10 papers, 2020 to 2023). A carcinoma that arises from epithelial cells of the prostate gland. "The same function is mediated by SNHG15 in prostate cancer that its overexpression significantly increases prostate cancer metastasis via EMT induction." (PMID 35773731, 2022). "In the Prostate cancer cells, SNHG15 was uncovered to participate in the EMT progress as down-regulated E-cadherin and up-regulated of N-cadherin expression." (PMID 32633324, 2020). "Moreover, lncRNA small nucleolar RNA host gene 15 (SNHG15) has been shown to play oncogenic roles in the progression of prostate cancer." (PMID 32351538, 2020). "Simply put, SNHG15 was involved in the regulation of the miR-338-3p/FKBP1A axis, thus encouraging the malignancy and tumorigenesis of prostate cancer." (PMID 37056344, 2023). "Mechanistically, SNHG15 down-regulates miRNA-338-3p by acting as ceRNA to upregulate KBP prolyl isomerase 1A (FKBP1A), leading to EMT-mediated metastasis of prostate cancer." (PMID 35773731, 2022).
colon cancer (9 papers, 2019 to 2025). "Certainly, these findings manifested a novel mechanism underlying the control of Slug stability, where SNHG15 interacted with and blocked Slug degradation along the ubiquitin-proteasome system, ultimately accelerating colon cancer progression." (PMID 37056344, 2023). "The highly expressed SNHG15 binds to the C-terminal zinc finger domain of Slug, which promotes the growth and metastasis of colon cancer." (PMID 40959095, 2025). "Transcription of SNHG15 was regulated by MYC oncogene, and overexpression of SNHG15 promoted the invasion of colon cancer by interacting with AIF." (PMID 37056344, 2023). "Small nucleolar RNA host gene 15 (SNHG15) maintains the stability of Slug in colon cancer cells by interacting with its zinc finger domain, which promotes the migration of colon cancer cells." (PMID 35506202, 2022). "Small nucleolar RNA host gene 15 (SNHG15) is also upregulated in colon cancer patients and correlates with poor prognosis." (PMID 33246471, 2020). "Although SNHG15 has been shown to be overexpressed in colon cancer through the analysis of TCGA database in Jiang's research, we examined the expression of SNHG15 in CRC tumor specimens and identified SNHG15 was significantly up‐regulated in CRC." (PMID 30945457, 2019). "Altogether, these results describe an important role of SNHG15 in promoting colon cancer and mediating drug resistance, suggesting its potential as prognostic marker and target for RNA-based therapies." (PMID 31014355, 2019). "Ectopic SNHG15 expression enhances tumor growth in a colon cancer xenografted model." (PMID 33246471, 2020). "SNHG15 overexpression accelerates the migration of colon cancer cells via interaction with the Slug domain, which impairs the ubiquitination and degradation of Slug and maintains its stability in colon cancer." (PMID 33246471, 2020).
papillary thyroid carcinoma (9 papers, 2018 to 2023). "In thyroid papillary carcinoma, exogenous overexpression of SNHG15 significantly blocked cell proliferation." (PMID 37056344, 2023). "With tumor-suppressing miR-200a as its target in papillary thyroid carcinoma, small nucleolar RNA host gene 15 (SNHG15) indirectly regulates expression of miR-200a’s target YAP1 oncogene and enhances disease progression." (PMID 35011635, 2021). "In summary, our findings demonstrated that SNHG15 serves as a competitively endogenous RNA (ceRNA) to regulate YAP1-Hippo signaling pathway by sponging miR-200a-3p in papillary thyroid carcinoma." (PMID 30237435, 2018). "stated that SNHG15 was highly expressed in papillary thyroid cancer (PTC)." (PMID 37056344, 2023). "Moreover, SNHG15 was confirmed to regulate YAP1-Hippo signaling pathway via sequestering miR-200a-3p in papillary thyroid carcinoma." (PMID 35101035, 2022). "Additionally, SNHG15 has been reported to act as a ceRNA to modulate the miR-200a-3p/YAP1-Hippo axis in papillary thyroid carcinoma." (PMID 33243205, 2020). "The present study focused on the biological role of SNHG15 in papillary thyroid carcinoma." (PMID 30237435, 2018).
lymph node metastasis (8 papers, 2020 to 2023). "SNHG15 overexpression was associated with tumor size, tumor node metastasis stage, and lymph node metastasis in patients with PC." (PMID 37189687, 2023). "Eleven studies comprising 937 patients were included to assess the association between the expression level of SNHG15 and lymph node metastasis." (PMID 32633324, 2020). "Clinicopathologic analysis revealed that high SNHG15 expression was associated with tumor differentiation, lymph node metastasis and tumor stage (p < 0.005), and patients with high SNHG15 expression had a shorter OS compared with the low SNHG15 expression group (p = 0.003)." (PMID 33924143, 2021). "High SNHG15 expression was associated with advanced TNM stage (OR = 3.05, 95% CI = 2.31–4.02, P < 0.00001), lymph node metastasis (OR = 3.20, 95% CI = 2.30–4.45, P < 0.00001), and distant metastases (OR = 5.05, 95% CI = 2.15–11.85, P=0.0002)." (PMID 32733556, 2020).
ovarian carcinoma (8 papers, 2021 to 2025). A malignant neoplasm originating from the surface ovarian epithelium. "declared that SNHG15 participated in the biological process of ovarian cancer by directly targeting and inhibiting the miR-18a expression and thus regulating the AKT/mTOR signaling pathway." (PMID 37056344, 2023). "What is more, SNHG15 has been reported to regulate the proliferation and metastatic of oral squamous cell carcinoma, ovarian cancer, and bladder cancer." (PMID 35733923, 2022). "Taken together, our results showed that SNHG15 promoted ovarian cancer cell proliferation through upregulated CDK6 via inhibiting mir-370-3p." (PMID 34734088, 2021). "In summary, SNHG15 was upregulated and predicted poor prognosis in ovarian cancer but the mechanism of SNHG15 remains undetermined." (PMID 34734088, 2021). "The results showed that SNHG15 was upregulated and predicted poor prognosis in ovarian cancer; in addition, SNHG15 promoted cancer cell proliferation through upregulated CDK6 via inhibited mir-370-3p." (PMID 34734088, 2021). "Herein, SNHG15 was identified by using GEO datasets and validated by ovarian cancer tissues and we investigated the clinical value and mechanism of SNHG15 in ovarian cancer." (PMID 34734088, 2021). "Herein, we initially identified that SNHG15 was upregulated in ovarian cancer based on published data, and then, we validated it in tumor tissues and cell lines." (PMID 34734088, 2021). "To demonstrate whether SHNG15 regulated CDK6 in ovarian cancer, we analyzed the CDK6 expression after SNHG15 knockdown, and in the si-SNHG15 group, CDK6 was lower than that in the si-NC group, indicating that SNHG15 regulated CDK6 expression in ovarian cancer." (PMID 34734088, 2021). "Our findings provided a new molecular mechanism of SNHG15 in ovarian cancer and may provide theoretical basis for the development of new clinical treatment strategies." (PMID 34734088, 2021). "Recently, SNHG15 was described as an oncogenic lncRNA in several cancers but the role of SNGH15 in ovarian cancer remains unclear." (PMID 34734088, 2021). "Taken together, our findings emphasize the important role of SNHG15 in ovarian cancer, suggesting that SNHG15 may be a promising target for ovarian cancer." (PMID 34734088, 2021). "Besides, high SNHG15 indicated poor prognosis in ovarian cancer." (PMID 34734088, 2021). "Furthermore, knockdown SNHG15 suppresses ovarian cancer proliferation and promotes apoptosis." (PMID 34734088, 2021). "SNHG15 was initially identified by using GEO datasets (GSE135886 and GSE119054) and validated by tumor tissues and the cell line, identifying that SNHG15 was upregulated in ovarian cancer." (PMID 34734088, 2021). "In conclusion, our study suggests that SNHG15 may be used as a prognostic indicator in ovarian cancer and reveals the SNHG15/miR-370-3p/CDK6 pathway in ovarian cancer." (PMID 34734088, 2021).
thyroid cancer (8 papers, 2020 to 2025). "Due to the fact that SNHG15 has only been reported as a tumor suppressor in thyroid cancer, the following functional studies concentrated on its involvement in cancer promotion." (PMID 37056344, 2023). "Detailed correlations with several parameters such as age, pathology classification, clinical stage, tumor size, and others, lead the authors to conclude that SNHG15 rather acts as an anti-tumor gene in thyroid cancer." (PMID 33572758, 2021). "Inhibition of SNHG15 by miR-510-5p was revealed to promote cell proliferation, migration, and invasion in thyroid cancer." (PMID 33572758, 2021). "Recent findings have shown that SNHG15 (Small nucleolar RNA host gene 15) is involved in proliferation, migration, and invasion of thyroid cancer and correlated with age, clinicopathological characteristics, and disease-free survival." (PMID 32760219, 2020). "Its overexpression is closely associated with clinical malignant phenotypes, suggesting that SNHG15 not only plays a crucial role in the initiation and progression of thyroid cancer but may also serve as a potential therapeutic target and prognostic biomarker." (PMID 41234719, 2025). "However, in two papers published by Liu and his colleagues, SNHG15 was reduced in thyroid cancer samples and acted as a tumor suppressor gene." (PMID 37056344, 2023). "However, only one report has found SNHG15 to be downregulated in thyroid cancer tissue samples and cells, suggesting its role as a tumor suppressor and the reduced expression of SNHG15 enhanced cell proliferation, migration, and invasion in vitro." (PMID 33243205, 2020). "SNHG15 was reported to be downregulated in thyroid cancer and acted as a tumor suppressor in TC." (PMID 32377223, 2020). "Interestingly, SNHG15 has an opposite expression in thyroid cancer, according to some researchers." (PMID 37056344, 2023). "In thyroid carcinoma, certain SNHG family members (e.g., SNHG7, SNHG15, SNHG12, SNHG14) have been reported as oncogenes, while others (e.g., SNHG3, SNHG5) may function as tumor suppressors—a discrepancy warranting further investigation." (PMID 41234719, 2025).
renal cell carcinoma (7 papers, 2020 to 2025). "It is reported that SNHG15 promotes the progression of renal cell carcinoma by regulating the NF-κB signaling pathway." (PMID 40959095, 2025). "For example, SNHG15 stimulates renal cell carcinoma proliferation and EMT by regulating the NF-κB signaling pathway." (PMID 37848987, 2023). "Meanwhile, another study has identified that SNHG15 facilitates renal cell carcinoma invasion and migration through the NF-κB signalling pathway and by inducing the EMT process." (PMID 33243205, 2020). "Finally, SNHG15 promoted renal cell carcinoma, gastric, pancreatic, breast, colon, prostate and non-small cell lung cancer, among others." (PMID 33333852, 2020). "The expression levels of small nucleolar RNA host gene 15 (SNHG15) may be involved in the NF-κB signaling pathway, induce the epithelial-mesenchymal transition process, and promote renal cell carcinoma invasion and migration." (PMID 33083486, 2020).
Stroke (6 papers, 2022 to 2025). Sudden impairment of blood flow to a part of the brain due to occlusion or rupture of an artery to the brain. "In contrast, silencing SNHG15 in a murine model of acute ischemic stroke has accelerated macrophage polarization toward the M1 phenotype, improving stroke-induced immunosuppression and decreasing susceptibility to stroke-associated infections." (PMID 40362498, 2025). "This further promotes the expression of SNHG15, thereby promoting the differentiation of macrophages to M2 type, which in turn aggravates post-stroke immunosuppression and leads to stroke-related infection." (PMID 36275741, 2022). "To further explore the potential mechanism of SNHG15 in stroke-induced immunosuppression, we investigated the response of SNHG15 to IL-4 or lipopolysaccharide (LPS) in sorted monocytes/macrophages by qRT-PCR." (PMID 34980176, 2022). "This study identified SNHG15 as a negative regulator of inflammation in stroke-induced immunosuppression, suggesting it as a novel biomarker and therapeutic target in stroke-associated infection." (PMID 34980176, 2022). "SNHG15 is a negative regulator of stroke-induced immunosuppressive inflammation." (PMID 36275741, 2022). "Thus, SNHG15 facilitated M2 macrophage polarization and thereby aggravated immunosuppression after stroke." (PMID 34980176, 2022). "SNHG15, which is an IL-4-induced lncRNA in macrophages, uniquely represses K63-linked ubiquitination of TRAF2 to promote M2 macrophage polarization and thereby attenuates inflammatory responses after stroke." (PMID 34980176, 2022). "The stroke-induced SNHG15 acted as a checkpoint to inhibit peripheral inflammatory responses." (PMID 34980176, 2022). "In addition, SNHG15 is an IL-4-induced macrophage LncRNA that uniquely inhibits K63 linked TRAF2 ubiquitination, thereby promoting M2 macrophage polarization and alleviating inflammatory response after stroke." (PMID 37153000, 2023). "(2022) found that SNHG15 was significantly highly expressed in monocytes in PBMCs of stroke patients, and IL-4 promoted the expression of SNHG15, LPS inhibited the expression of SNHG15, and SNHG15 could partially inhibit the transformation of macrophages to M1 type." (PMID 36275741, 2022). "For example, the combination of miR-4510, miR-27a-5p, miR-1246, and wiRNA_2048 expression as a disease biomarker was found to have more than 90% accuracy in detecting mTBI, while the combination of linc-DHFRL1-4, SNHG15, and linc-FAM98A-3 expression had more than 80% accuracy in detecting stroke." (PMID 36443964, 2023).
bladder cancer (5 papers, 2021 to 2025). "Of note, H19, UCA1 and SNHG15 have been recently studied in bladder cancer." (PMID 40461454, 2025). "These insights not only offer new avenues for molecular classification and non-invasive prognostic assessment of bladder cancer (e.g., the SNORS model), but also suggest potential targeted therapies, such as inhibiting SNHG1 or targeting SNHG15-SEs." (PMID 41301542, 2025). "After the silencing of SNHG15, the expressions of E-cadherin and β-catenin were memorably increased, while the N-cadherin and Vimentin were decreased, suggesting that SNHG15 was also involved in the development of OSCC, bladder cancer, BC, and OC." (PMID 37056344, 2023). "For interactions between super enhancers and signaling pathways: SNHG15 super enhancers recruit the transcription factor FOSL1 to initiate their transcription, while promoting ADAM12 expression via the WNT/CTNNB1 pathway, thereby accelerating bladder cancer cell proliferation and metastasis." (PMID 41301542, 2025).
cervical cancer (5 papers, 2022 to 2025). A primary or metastatic malignant neoplasm involving the cervix. "In cervical cancer, both in vitro and in vivo studies have shown that SOX12-induced SNHG15 promotes cervical cancer tumorigenesis and resistance to cisplatin via the miR-4735-3p/HIF1a pathway." (PMID 37056344, 2023). "SNHG15 is upregulated in cervical cancer tissues and promotes cervical cancer progression via the miR-4735-3p/HIF1a axis." (PMID 35406713, 2022).